TNF (tumor necrosis factor)
Diseases named in the same sentence as TNF in open-access papers (continued):
Sharing a sentence is not in itself a finding about the gene and the disease.
heart failure (continued). "As previous studies have noted, the induction of specific cytokines, such as IL-6 and TNF-α, plays a detrimental role in the development of adverse ventricular remodeling and subsequent heart failure, contributing to conditions such as cardiac hypertrophy and impaired myocardial contractility." (PMID 39805484, 2025). "Heart failure (HF) is frequently marked by persistent inflammation, characterized by increased levels of pro-inflammatory cytokines such as interleukin-6 (IL-6), interleukin-1b (IL-1b), and tumor necrosis factor alpha (TNF-a) in the blood of HF patients." (PMID 39736852, 2025). "Emerging reports highlight that TNF inhibitors may contribute to heart failure even in younger individuals with rheumatologic conditions undergoing long-term therapy." (PMID 41018385, 2025). "In this study, it was found that overexpression of PLAC8 rescued the high expression of these markers, reversed the progression of myocardial infarction to heart failure, reduced cardiomyocyte injury, and lowered the expression of the inflammatory markers TNF-α and IL-1β in serum." (PMID 40471391, 2025). "Patients without preexisting cardiac disease receiving anti-TNF agents exhibit a very low risk of developing heart failure." (PMID 41155452, 2025). "And 2 RCTs analyzed the levels of TNF-α and included 178 patients with heart failure." (PMID 41179565, 2025). "Similarly, TNF-α inhibitors, including agents like infliximab and etanercept, have shown promise in reducing inflammation and improving cardiac function in heart failure patients, which in turn reduces arrhythmic events." (PMID 40901119, 2025). "Our findings point to two clinical considerations: a potential rationale for a more permissive attitude toward biologic therapy (including anti-TNF agents) in patients with heart failure, and the need for particular caution when contemplating azathioprine in the same setting." (PMID 41155452, 2025). "To further elucidate the specific mechanisms through which LA and ALA improve heart failure symptoms, we conducted exploration testing on several candidate pathways provided in the literature, including inflammatory response (TNF-α, VCAM-1) and vasodilation (VEGF)." (PMID 41154077, 2025). "Inhibition of matrix metalloproteinases (MMPs)induction and myocardial remodeling by TNF-α blocking proteins in a dogpacing-induced heart failure model confirmed their ability to block local matrixmetalloproteinase production in cardiac TNF-α overexpressing mice." (PMID 39742244, 2024). "Additionally, cytokines are implicated in the pathogenesis of SFTS, with elevated levels of IL-6, IL-10, TNF-α, and interferon-γ reported in severe cases, including those involving heart failure, compared to healthy adults." (PMID 38389047, 2024). "It is an anti-IL-17 not contraindicated in patients with heart failure; moreover, differently from anti-TNF, the risk of reactivation of latent tuberculosis seems to be a concern." (PMID 39336506, 2024). "Other relevant adverse reactions with anti-TNF-α class are urinary tract infection, back pain, arthralgia, pruritus and erysipelas, invasive fungal infections, lymphoma, heart failure, cytopenia, induction or exacerbation of demyelinating disease and lupus-like syndrome (e.g., infliximab)." (PMID 38521706, 2024). "It is critical to note that TNF inhibitors are contraindicated in the context of heart failure." (PMID 38883113, 2024). "In this work, we studied how Tumor necrosis factor alpha (TNFa), as a key component of the pro-inflammatory microenvironment in damaged myocardium from ischemic injury and heart failure, may affect the secretome content of CDCs and their angiogenic properties." (PMID 38068898, 2023). "Bacterial lipopolysaccharide (LPS), endotoxin, viral antigens, immune complexes, IL-1, and TNF-α itself can all trigger the release of TNF-α; additionally, some pathophysiological circumstances (inflammation, trauma, heart failure) can stimulate its production." (PMID 37833861, 2023).
heart failure (continued). "The ATTACH study reported that the use of anti-TNF therapy increased mortality or worsened heart failure in patients with moderate to severe chronic heart failure, especially those with an ischemic etiology, but the RENAISSANCE and RECOVER clinical trials did not confirm this for etanercept." (PMID 37763669, 2023). "Firstly, comorbidities (such as heart failure for anti-TNF antibodies and renal or hepatic failure for antibiotics) and frailty might affect treatment choice, constituting contraindications to or discouraging the use of immunomodulant drugs." (PMID 38137823, 2023). "Based on the results of the Anti-TNF Therapy Against Congestive Heart Failure (ATTACH) trial showing an association between high-dose infliximab and worsened heart failure, TNFi is contraindicated in New York Heart Association class III and IV heart failure." (PMID 38077350, 2023). "Serum levels of TNF-α are positively correlated with the severity of heart failure." (PMID 38270118, 2023). "The ATTACH study reported that anti-TNF therapy increased mortality or worsened heart failure in patients with moderate to severe chronic heart failure, especially those with an ischemic etiology, but the RENAISSANCE and RECOVER clinical trials did not confirm this for etanercept." (PMID 37763669, 2023). "Accordingly, an increment in the pro-inflammatory cytokine concentrations, similar to interleukin 6 (IL-6) and tumor necrosis factor, occurs, thereby impairing both renal and myocardial functions, which, in turn, leads to the speeding up of the progression of heart failure (HF)." (PMID 37529809, 2023). "Interestingly, we found that proinflammatory cytokine TNF-α positively correlated with high sensitivity C-reactive protein in patients with advanced heart failure undergoing heart transplantation." (PMID 37745103, 2023). "Additionally, a similar traditional Chinese medicine, Xinyin Tablet has shown to alleviate heart failure by reducing serum levels of TNF-α and IL-6 and improving cardiac ultrastructure." (PMID 37919806, 2023). "A similar study conducted primarily in patients with systolic HF across varying stages concluded that the levels of inflammation such as IL-6, CRP, adiponectin, endothelin, and TNF-a, and oxidative stress, such as isoprostane increased along with the severity of heart failure." (PMID 36938237, 2023). "It is also known that in MI subsequent to reduced or stoppage of coronary flow, there is an elaboration of TNF‐α in the early stages which may play an important role in cardiac remodeling and heart failure." (PMID 35938295, 2022). "It was established that cytokines such as TNF-α, IL-1β, and IL-6 play an important role in the development of heart failure in several clinical scenarios, and some attempts were even made to regulate their effects on heart tissue, yet no conclusive treatment proposals were established." (PMID 35269577, 2022). "TNF-α, for instance, is elevated in severe heart failure and may induce pulmonary edoema, left ventricular dysfunction, and cardiomyopathy in experimental settings." (PMID 35813433, 2022). "One can speculate that glutathione status determines the adverse effects of TNFα in cardiac failure and that TNFα antagonism may be achieved by glutathione supplementation." (PMID 35406812, 2022). "TNF-α, IL-1 and IL-6 are among the pro-inflammatory cytokines that are increased in heart failure." (PMID 36547425, 2022). "For heart failure, only one study compared tumor necrosis factor (TNF) antagonist use with methotrexate (MTX) monotherapy and this demonstrated an increased risk in the TNF antagonist users." (PMID 35915691, 2022). "TNFα specifically triggers production of mitochondrial ROS in cardiac myocytes, which may lead to mitochondrial DNA damage and development of heart failure." (PMID 35883637, 2022).
heart failure (continued). "Therefore, the present study aimed to investigate the relationship between soluble TNF-α receptors—sTNFr1 and sTNFr2—and the severity of heart failure and inflammation to evaluate the potential use of TNF-α inhibitors in the management of heart failure." (PMID 36428528, 2022). "TNF and IL-6 biomarkers have been connected to the severity of heart failure, suggesting that they could be employed as biomarkers in the future." (PMID 35813433, 2022). "Beside the classic marker that is CRP (which is an independent prognostic factor for adverse events in patients with heart failure) or NT-proBNP, an increased concentration of TNF- α, ST2, IL-1, IL-6, IL-8, Galectin-3 (Gal-3), and growth differentiation factor 15 (GDF15) was also observed." (PMID 35269577, 2022). "The levels of TNF-α and IL-7 were significantly higher in the saliva of patients with heart failure and normal saliva secretion compared to the controls, as was the content of IL-1β, TNF-α and IL-7 in the saliva of patients in the study group with hyposalivation compared to the control group." (PMID 36300113, 2022). "Proinflammatory cytokines (TNF-α, sTNFR-1, and sTNFR-2) were powerful independent predictors of chronic heart failure patients, and the inflammatory response was a core common factor in all stages of cardiac failure in patients." (PMID 35425840, 2022). "Therefore, we reviewed the history of TNF-α antibodies in drug development for heart failure and RA as a reference to identify the reason for such a warning in the recommendations and its applicability to ICI-induced myocarditis." (PMID 35844550, 2022). "TNF-α and IL-6 have been suggested as potential markers of heart failure in a number of studies." (PMID 35813433, 2022). "Reactive oxygen species activate nuclear factor-kappa B, which leads to increased production of C-reactive protein, tumor necrosis factor-α, and interleukin-6, along with adhesion molecules such as E selectin, CD15, and CD32 that can cause endothelial damage, CHD, heart failure." (PMID 35287580, 2022). "TNF-α stimulates myostatin expression through the NF-κB-involved pathway in heart failure." (PMID 35400955, 2022). "TNF α has a negative inotropic effect and its level is associated with the severity of heart failure and the extent of myocardial damage." (PMID 35683362, 2022). "According to the US National Data Bank for Rheumatic Diseases, heart failure was significantly less common in anti-TNF-treated patients (2.8%) than in patients treated with disease-modifying antirheumatic drugs (DMARDs) (3.9%) after adjustment for demographic characteristics." (PMID 35844550, 2022). "The addition of heart failure was associated with an additional increase in the level of C-reactive protein, TNF-α, and IL-6 in the blood, regardless of patients’ sex." (PMID 35997392, 2022). "While blocking TNF-α in heart failure (HF) has been proven contraindicated in symptomatic (NYHA III and IV) patients, anti-TNF-α may be a promising approach to prevent the early stages of cardiotoxicity from anti-PD-1 immunotherapy." (PMID 35432346, 2022). "Infliximab, one of the TNF (tumor necrosis factor) antagonists, was also used to reduce irAEs, however, TNF antagonists may cause heart failure or exacerbate existing disease." (PMID 34987517, 2021). "Interleukin-6, TNF-α and adiponectin correlated with heart failure severity parameters." (PMID 34685378, 2021). "Also, a decreasing in the level of chronic inflammatory markers of heart failure progression like TNF-α is observed." (PMID 34162424, 2021). "Long-term overstimulation of TNF leads to an impaired ability of the β-adrenergic receptor (β-AR) to respond to natural agonists, resulting in systolic dysfunction, cardiac hypertrophy, and induction of cardiomyocyte apoptosis in patients with heart failure." (PMID 35187113, 2021).
heart failure (continued). "TNF alpha is one of many pro-inflammatory cytokines that has been suspected to play a pivotal role in the pathogenesis and development of cardiovascular disease and heart failure (HF) in RA patients." (PMID 34660128, 2021). "Tumor necrosis factor alpha may contribute to the pathology of postoperative myocardial infarction, postischemic cardiac dysfunction, and heart failure." (PMID 34250089, 2021). "The beneficial cardiovascular effects seen with IL-1 blockers (anakinra and canakinumab) are in stark contrast with the lack of benefits with methotrexate, and the dose-dependent increase in heart failure-related mortality seen with the TNF-α blocker (infliximab)." (PMID 34749739, 2021). "Tumor necrosis factor α (TNF-α) was the first cytokine found to be significantly elevated in the serum of patients with heart failure, which could directly induce myocardial apoptosis and necrosis, bringing about ventricular adverse remodeling." (PMID 34869661, 2021). "However, prolonged activation of NF-κB appears to be detrimental and promotes heart failure by eliciting signals that trigger chronic inflammation through enhanced elaboration of cytokines including TNF-α and IL-6, leading to apoptosis." (PMID 33809417, 2021). "One of the reasons for Klotho downregulation in type 2 CRS maybe the increase of circulatory tumor necrosis factor-α induced by heart failure." (PMID 33460402, 2021). "These molecular events have been associated with the progression of this pathophysiology, via Fas (sFas), Fas ligand (sFas-L), TNFα (tumor necrosis factor α), and IL-6 (interleukin-6), which are negatively correlated with fractional shortening and result in heart failure." (PMID 34445422, 2021). "The damage, repair and remodeling of myocardium are the important link in the occurrence and development of heart failure, of which immune/inflammatory cells (neutrophils, lymphocytes, etc.)and the inflammatory factors (tumor necrosis factor, interleukin-6, etc.)released by them are involved." (PMID 34869661, 2021). "Additionally, in heart failure rats, TNF-alpha inhibition reduced chronic catecholamine-induced stress in the paraventricular nucleus and ameliorated cardiac function." (PMID 34966735, 2021). "This suggests that the sustained high concentration of MBNL1 may contribute to heart failure via Myocardin and TNF‐α." (PMID 33295096, 2021). "There was the decrease in cardiac failure parameters such as: creatine kinase, MB isoenzyme of creatine kinase and lactate dehydrogenase, as well as the extenuation of cardiac mRNA expression for tumor necrosis factor α (TNF-α) and interleukin 6 (IL-6)." (PMID 34576213, 2021). "Given the critical role of TNF-α in triggering AKI-related cardiovascular events and regulating myocardial contractility, several large multi-center trials have been performed to evaluate whether the TNF-α inhibitor etanercept could prevent heart failure." (PMID 32561688, 2020). "TNFα blockade not only failed, but also led to the disease worsening in cases of heart failure." (PMID 33708123, 2020). "Our previous animal experiments showed that FXHJ could effectively reduce the level of TNF-α in rats with heart failure, improve the expression of the BCL2 gene, and thus inhibit a variety of myocardial cell apoptosis pathways." (PMID 33273955, 2020). "Studies have shown that increased TNF-α levels exacerbate heart failure." (PMID 33273955, 2020). "Targeting tmTNF-α processing may be more useful than TNF-antagonist for treatment of hypertrophy and heart failure." (PMID 33270628, 2020). "Instead, such targeted immunomodulatory therapeutic intervention was considered in heart failure patients, but the failure of anti-TNF-α therapy could be explained by the cardioprotective properties of TNF-α in the failing heart." (PMID 33053859, 2020). "Interestingly, the potential use of IL-1 inhibition is in contrast to the results of TNFα inhibitors in the treatment of heart failure." (PMID 33708123, 2020).
heart failure (continued). "SI was shown to increase the expression levels of Nrf2 and SOD and to reduce the expression of C-reactive protein, 8-isopropanol, MDA, IL-6, and TNF-α in patients with heart failure, improving the antioxidant capacity of patients with IC by upregulating Nrf2 and treating heart failure." (PMID 33062142, 2020). "The Yin and Yang of TNF-α signaling in heart failure: this Primer explores the history of failure of TNF-α antagonistic therapy in heart failure and how a recent study suggests that inhibition of TNF-α converting enzyme TACE might be a way out of this dilemma." (PMID 33296366, 2020). "Indeed, previous studies have reported a strong relationship between circulating soluble TNF and mortality in patients with heart failure." (PMID 33330676, 2020). "However, various studies have shown that cardiac function can be disturbed in patients on TNF inhibitors and are therefore a contraindication in patients with heart failure." (PMID 33193432, 2020). "This showed that increased TNF-alpha level in the DOX-treated group could be due to induction of heart failure by DOX." (PMID 33203171, 2020). "TNF and IL-6 serum levels correlate with heart failure severity and prognosis." (PMID 33344515, 2020). "Providing a potential mechanistic explanation for the ineffectiveness of TNF-α blockade in heart failure, novel findings demonstrate that the membrane-bound precursor form of TNF-α, transmembrane TNF-α (tmTNF-α), mediates cardioprotective effects during pressure overload-induced cardiac remodeling." (PMID 33296366, 2020). "By reducing TNF-α, the three extracts demonstrated potential safety in heart failure conditions." (PMID 33339902, 2020). "In addition to traditional risk factors, TNF-α has also been significantly associated with an increased risk of heart failure in CKD and high levels of TNF-α have been associated with markers of malnutrition and inflammation, as well as predicting mortality." (PMID 31906008, 2019). "However, data regarding cardiac failure in patients treated with anti-TNF-alpha agents are inconclusive." (PMID 31261785, 2019). "Indeed, data from a clinical trial show that in patients with heart failure the treatment with Infliximab, a chimeric monoclonal antibody to TNF-α, or Etanercept, a soluble TNF receptor, increased mortality." (PMID 30935055, 2019). "This confirmed that CGA significantly suppressed the TAC‐induced upregulation of TNF‐α, suggesting CGA has cardioprotective effects and might mitigate the overexpression of TNF‐α in a TAC heart failure mouse model." (PMID 31033175, 2019). "However, recently it was reported that circulating pro-inflammatory cytokines TNF-α and IL-6 decreased significantly after 3 months of PD and remained low at 6 months of follow-up in patients with heart failure undergoing PD due to overflow." (PMID 31612137, 2019). "Anti-TNF could be used for patients with an ejection fraction > 50% and well-compensated heart failure (NYHA class I–II)." (PMID 31025187, 2019). "Nevertheless, IL-10 is considered as a cardio-protective cytokine and increased levels of IL-10 in heart failure may be seen as a compensatory mechanism to counter deleterious effects of cytokines, such as TNF-α or IL-6." (PMID 30177883, 2018). "Moreover, a significant correlation between the serum levels of TNF-α and the severity of heart failure has been reported." (PMID 29511093, 2018). "Notably, a concordant reduction in TNF-α receptors on the cardiac myocytes was noticed in heart failure patients too, which was attributed to the high circulating levels of TNF-α." (PMID 29487525, 2018). "Indeed, disappointing results of anti-inflammatory strategies have been shown in double-blind clinical trials targeting TNF-α in patients with heart failure." (PMID 29511093, 2018). "Additionally, multiple studies have shown high levels of pro-inflammatory cytokines such as TNF-α, IL-6, and IL-1β in the peripheral circulation and heart of cardiac failure patients." (PMID 30558188, 2018).